SOX2 (SRY-box transcription factor 2)
Diseases named in the same sentence as SOX2 in open-access papers (continued):
Sharing a sentence is not in itself a finding about the gene and the disease.
tumor (continued). "BIN1 overexpression correlated with reduced expression of key stemness and EMT markers, including Myc, ALDH1, OCT4, EPCAM, KLF4, NANOG, SOX2, and decreased tumor sphere-formation capabilities, suggesting EMT inhibition." (PMID 40016843, 2025). "Experimental induction of BRAFV600E in Ras + β2-tanycytes of adult mice led to dedifferentiation and formation of PCP-like tumors, characterized by SOX2/SOX9 + stem-like cells in the tumor core and a peripheral Ki67 + proliferative zone." (PMID 40696244, 2025). "In vivo, LPCAT1 enhanced tumor growth, lung metastasis, and cholesterol metabolism, while these effects were counteracted by SOX2 inhibition." (PMID 41358198, 2025). "For evaluating MSC migration into the tumors, MSC marker CD74- or sex determining region Y box 2 (SOX2)-positive cells in tumor tissues were detected by immunohistochemistry." (PMID 39940960, 2025). "Collectively, our findings support the anti-tumor effect of Akt/Sox2-targeting PCA, suggesting a novel utilization of PCA in BC therapy." (PMID 40076435, 2025). "The analyses identify 3,447 tumor‐specific oncogenic enhancers (SOEs) enriched for master transcription factors (SOX2, TP63, KLF5, GRHL2) that orchestrate malignant programs." (PMID 40899632, 2025). "After loss of Sox2, LMX1A and Ki-67 expression was greatly reduced, whereas the expression of LMX1B was abolished in Sox2-deficient CP tumor cells from Lcre;NICD1;Sox2cko embryos." (PMID 40128799, 2025). "By selecting tissue regions based on histology and segmenting tumor (SOX2+) and TAM (IBA1+) compartments, we reduced sampling variability across samples." (PMID 40960500, 2025). "SOX2 also impacts various tumor biological behaviors, including cell proliferation, invasion, metastasis, resistance to apoptosis, and treatment resistance." (PMID 40821114, 2025). "Our findings indicate that SOX2 expression in plasma strongly correlates with Ki-67 levels (r = 0.72, p < 0.001), supporting its role as a marker of tumor cell proliferation." (PMID 40674376, 2025). "Deletions in CDKN2A (cyclin-dependent kinase inhibitor 2A) impair the cell cycle checkpoint, whereas aberrant activation of stem cell markers such as SRY-Box transcription factor 2 (SOX2) supports tumor cell self-renewal and invasion." (PMID 40628732, 2025). "Sox2-expressing stem cells have been observed in atypical MGs and in stem cells cultured from these tumours." (PMID 39316249, 2025). "This study aims to quantify SOX2, PIWI proteins, and MALAT1 in plasma samples and evaluate their correlation with IHC-based tumor markers to assess their diagnostic potential." (PMID 40674376, 2025). "It has been established that SOX2 functions as a critical marker of cancer stem-like cells (CSCs), a specific subpopulation of tumor cells that possess self-renewal capacity and therapy resistance." (PMID 40699660, 2025). "In IHC staining with antibodies to the oligodendrocyte marker protein Olig2 and the mature astrocyte marker GFAP, as well as the stem cell marker Sox2, a large number of Olig2+ and Sox2+ cells were observed in the tumor node relative to the peritumoral zone." (PMID 41009560, 2025). "In this model, over 90% of proliferative tumor cells were positive for SOX2 (a stem cell marker) and pERK1 + /ERK2 + (downstream mediators of BRAF and major effectors of MAPK)." (PMID 40696244, 2025). "In vivo experiments further supported these findings, showing that SOX2 down-regulation significantly inhibited tumor growth and enhanced the sensitivity of tumors to chemotherapy." (PMID 40821114, 2025). "The analysis of SOX2 expression in formalin-fixed, paraffin-embedded material, revealed that the SOX2 expression was present in primary tumor samples." (PMID 40918157, 2025). "We identified tumor RG-like (NEShigh; SOX2+), NProg-like (NESlow/−; SOX2+) and Nb-like (SOX2−; MAP2+) cells in protein staining." (PMID 40562749, 2025).
tumor (continued). "High SOX2 levels are correlated with tumor aggressiveness and poor prognosis, making it a target of interest for therapeutic intervention." (PMID 40628732, 2025). "Only TMA cores corresponding to high-purity SOX2+ tumor regions were included, to ensure consistency with the GeoMx filtering strategy." (PMID 40960500, 2025). "This upregulation was linked to anti-tumor activity in gastric cancer cells, possibly through the reactivation of tumor-suppressive pathways regulated by Sox2." (PMID 40650308, 2025). "We showed the expression levels of NANOG, BMI1, and SOX2, which are the pluripotency transcription factors involved in the regulation of CSCs, strongly grew along with advanced pathological tumor grade, whereas OCT4 was unchanged." (PMID 40016182, 2025). "Not only does SOX2 specify direct squamous maturation, but its expression also inhibits proliferation signals and tumor suppressor mechanisms that have been shown to be required for subsequent CDX2-mediated intestinalization of esophageal squamous epithelium." (PMID 40587339, 2025). "The BRAF V600E mutation activates the MAPK/ERK pathway, driving abnormal proliferation and impaired differentiation of SOX2 + cells, which likely serve as the cellular basis for tumor initiation." (PMID 40696244, 2025). "The regulatory influence exerted by HIF-1α on the SOX2/OCT4 signaling pathway plays a significant role in tumor cell self-renewal and differentiation." (PMID 39781344, 2025). "SOX2 was found to be elevated in both the tumor core and close margin, correlating with tumor size and lymph node involvement, indicating a potential role in local dissemination." (PMID 40227667, 2025). "In cancer cells, SOX2 is integral to the regulation of stem cell characteristics and cellular proliferation, which are regarded as critical factors driving tumor occurrence." (PMID 39976818, 2025). "Specifically, SOX2 is involved in regulating tumor stem cell properties, the cell cycle, proliferation, metastasis, and treatment resistance." (PMID 40821114, 2025). "Pseudotime trajectory analysis indicated that NOTCH-driven CP tumor arises from bipotential glial progenitors and retains a progenitor-like signature characterized by an enhanced SOX2 profile." (PMID 40128799, 2025). "Conversely, Sox2 loss resulted in significantly reduced LMX1A expression, whereas LMX1B was lost in Sox2-deficient tumor cells after birth." (PMID 40128799, 2025). "The in vitro validation experiments further emphasised the importance of tumour molecular characteristics—specifically SOX2 dependency—in determining therapeutic response." (PMID 41388088, 2025). "Analysis of pooled data uncovered over 10 000 SOX2-bound peaks in promoters/enhancers, gene bodies, and intergenic regions in tumor cells." (PMID 40128799, 2025). "Tumor cells can acquire or reinforce stem-like properties through reactivation of pluripotency-associated transcription factors such as OCT4, SOX2, Nanog, KLF4, and Myc." (PMID 41204384, 2025). "αEGFR‐t‐SOX2‐cLNPs achieved specific delivery to tumor cells, resulting in 90% tumor growth inhibition of HNSCC‐bearing mice." (PMID 39736115, 2025). "The CO portion of the GCOAs was rich in both NeuN‐ and TUJ1‐positive neurons, as well as SOX2‐positive neural progenitor cells, which were in contact with the invading tumor cells." (PMID 39473365, 2025). "Frequently upregulated in MCC, particularly in MCV-positive tumours, SOX2 fosters a stem-like state that promotes tumor progression, metastasis, and therapy resistance." (PMID 40589575, 2025). "In vivo, xenograft model indicated that knockdown of MYH9 significantly inhibited the PGK1‐mediated tumour growth and the expression of Snail, SOX2 and β‐catenin." (PMID 40534132, 2025). "Mouse models with Sox2 overexpression combined with Nkx2-1 and Lkb1 loss (SNL model) demonstrated enhanced adeno-to-squamous differentiation of tumors as well as tumor-associated neutrophil (TAN) recruitment." (PMID 40327401, 2025).
tumor (continued). "Both genes are necessary and sufficient to support SOX2 functions in tumor cell proliferation, and thus comprise an important part of the SOX2-dependent progenitor-like program in tumor development." (PMID 40128799, 2025). "SOX2 regulates the fate of cancer stem/progenitor cells, contributing to tumor initiation, development, and metastasis." (PMID 40821114, 2025). "SOX2 represses the TET2 demethylase, resulting in reduced levels of 5hmC, a key DNA modification associated with tumor suppression." (PMID 40565099, 2025). "Intrinsically, the tumor-driving factors SOX2 and NKX2–1 have opposing regulatory effects on TAN accumulation, suggesting that cancer cell intrinsic factors also shape TIME, challenging the notion that tissue type alone determines TIME." (PMID 40568576, 2025). "Our in vivo experiments demonstrated that BAPN-induced ECM softening significantly suppressed tumor growth by inhibiting the PIEZO1–DOT1L–NANOG/SOX2 axis." (PMID 41533929, 2025). "By dynamically altering cell states, inducing treatment escape‐associated TFs (such as SOX2, ASCL1), and activating pathways like PI3K/AKT and MYC, the tumour further enhances its ability to adapt to immune attack and metabolic stress." (PMID 40847555, 2025). "The authors have demonstrated that the UPF1/LINC00963/miR-508-5p/SOX2 axis has potential value in modulating chemoresistance and tumor progression in EC." (PMID 40804837, 2025). "Initially, we assessed the impact of SOX2 knockdown on tumor sphere formation and observed that SOX2 knockdown in 143B and HOS cells significantly reduced tumor sphere formation." (PMID 39994220, 2025). "SOX2, a key transcription factor in preserving stem cell traits, plays a role in the initiation and malignant progression of multiple tumor types." (PMID 41425729, 2025). "In fact, SOX2 expression is much higher in tumor tissues than in normal tissues, and a high level of SOX2 correlates with poor prognosis." (PMID 41463190, 2025). "HIF‐1α enhances the secretion of VEGF by stromal cells (such as CAFs and endothelial cells), which not only promotes angiogenesis but also activates Myc and SOX2 signalling within tumour cells." (PMID 40847555, 2025). "By measuring Sox2-positive cells, we found very high densities in the tumor bulk (over 4000 cells/mm2) but much lower levels at the invasive margin (about 30 cells/mm2) and a clear gradient in the corpus callosum (3010 to 1.5 cells/mm2 across 1 mm)." (PMID 41375052, 2025). "The tumor sphere assay indicated that SOX2 overexpression not only increased the number of tumor spheres but also markedly enlarged their sizes." (PMID 39994220, 2025). "H3K9la has been identified as a critical mark at promoters of pluripotency genes (e.g., OCT4, SOX2), driving cellular reprogramming and stemness maintenance in varying tumor contexts." (PMID 41583433, 2025). "Tumor regions with high densities of SOX2+ tumor cells and IBA1+ TAMs were selected for spatial profiling, enabling a focused profiling of PD-1 blockade-associated gene expression patterns within these cell types." (PMID 40960500, 2025). "Signaling through the protein CCN2 (also known as CTGF) released by tumor cells can activate surrounding fibroblasts, inducing expression of the stemness marker Sox2 in them and turning them into activated CAFs." (PMID 40806546, 2025). "These cells, marked by proteins such as prominin-1 (CD133), SRY-box transcription factor 2 (SOX2), and polycomb complex protein BMI-1 (BMI-1), contribute to therapy resistance and tumor recurrence." (PMID 40722337, 2025). "This process is regulated by key pathways such as TGF-β and Wnt/β-catenin, which modulate transcription factors like Snail and SOX2, promoting tumor aggressiveness." (PMID 40243417, 2025). "Li et al136 demonstrated that transforming growth factor beta (TGF-β) signaling enhances the invasiveness of SOX2-driven tumor cells, a process potentially mediated through the induction of EMT." (PMID 40821114, 2025).
tumor (continued). "We observed a significant reduction in the number of Ki67, Olig2- and SOX2-positive cells in the mubritinib-treated mice, indicating that mubritinib alters proliferation and stemness in GB tumours in vivo." (PMID 39901019, 2025). "Similar to lineage‐defining factors like NKX2‐1 and SOX2, tumour lineage is governed by binary epigenetic regulation." (PMID 40847555, 2025). "Recent single-cell RNA sequencing studies have identified a positive correlation between higher SOX2 expression and tumor progression." (PMID 41145440, 2025). "Reduction in cancer stem-like cell population was further confirmed by using a SORE-GFP reporter where SOX2 and Oct4 response elements drive GFP expression previously shown to associate with elevated self-renewal and tumor initiation capacities." (PMID 40136647, 2025). "This approach not only inhibits SOX2's tumor-promoting role but also presents new potential targets for cancer therapies." (PMID 40821114, 2025). "SOX2 has been recognized as an oncogenic factor capable of enhancing tumor cell growth and dissemination." (PMID 41023726, 2025). "Combining SOX2 overexpression with common tumor suppressors PTEN and CDKN2A leads to LUSC-like tumors in basal, alveolar type 2, and club cells." (PMID 40327401, 2025). "Specifically, when SOX2 levels attain physiological ranges, it promotes tumor proliferation and metastasis; conversely, exceeding these endogenous levels in vivo results in the suppression of tumor growth and spread." (PMID 39976818, 2025). "The expression of SOX2 in OSCC was found to be higher both in the tumor and the peritumoral vessels." (PMID 40568269, 2025). "The complex signaling network involves numerous molecules that interact with SOX2 to regulate various biological processes in tumor cells, promoting malignant tumor progression." (PMID 40821114, 2025). "They showed that mice that overexpressed ID4 and SOX2 had significantly higher tumor weight after carmustine treatment when compared to wild-type mice." (PMID 39861164, 2025). "Given its established function as a tumor stem cell marker, Sox2 likely contributes to the maintenance of a self-renewing, proliferative cell population within these lesions." (PMID 41176605, 2025). "There was a statistically significant correlation between SOX2 and the age (64 years, p < 0.025), the pathological tumor size (T1/T2 vs. T3/T4, p < 0.001), the clinical stage (I/II vs. III/IV, p < 0.004), and extracapsular spread (Ecs0 vs. Ecs+, p < 0.031)." (PMID 39180200, 2025). "Consistently, RT-qPCR and RNA-seq studies using tumor bulk showed significantly increased Lmx1a and Lmx1b expression, along with increased Sox2 levels, compared to wild-type CP from birth to adult stage." (PMID 40128799, 2025). "To further elucidate the molecular basis underlying decursin’s anti-tumor effects, we examined two malignancy-associated proteins (TP63 and SOX-2) under varying treatment durations (0 h, 24 h, 48 h, and 72 h) and concentrations (0 μM, 10 μM, 20 μM, and 40 μM)." (PMID 40508204, 2025). "In MGs, Sox2 is preferentially expressed in high-grade tumours and correlates with clinical behaviour, with expression being highest in grade 3 tumours." (PMID 39316249, 2025). "Lately SOX2 and SOX9, transcription factors associated with stemness‐like phenotypes of cancer cells, have been linked to tumor growth, metastasis, and resistance to therapy." (PMID 39180200, 2025). "In MB, SOX2 protein expression is critically involved in tumor development, especially in the SHH molecular subgroup." (PMID 39851500, 2025). "To investigate the tumor-suppressive mechanisms of decursin, we performed Western blot analysis of ESCC-associated oncoproteins TP63 and SOX-2." (PMID 40508204, 2025).
tumor (continued). "Immunohistochemistry demonstrated that tamoxifen treatment successfully deleted Sox2 expression in tumor cells." (PMID 40571713, 2025). "These molecules and pathways regulate SOX2 expression and activate downstream effects that influence tumor cell behaviors, such as proliferation, migration, and invasion." (PMID 40821114, 2025). "Epithelial CSCs were characterized by the expression of the CSC marker SOX2, fast cell growth, and strong self-renewal ability in vitro, together with massive tumor formation in vivo." (PMID 38398077, 2024). "SOX2 was positive in a higher proportion of WDLD tumours compared with those meeting WHO lineage criteria, 7/10 (70%) v 10/42 (23.4%), P = 0.005." (PMID 38483762, 2024). "This study explores the inverse association of SOX2/SOX9 and their distinct expression in tumors, influencing the tumor microenvironment and radiotherapy responses." (PMID 38275880, 2024). "Collectively, these findings and the demonstration that MUC1 associates with expression of ∆Np63, SOX2, and NOTCH3 in individual HNSCC tumor cells indicate that MUC1-C is a common effector of the HNSCC CSC state." (PMID 38619287, 2024). "After that, they were co-cultured with ATC cells, Tumor spheroids were greatly aided by this procedure, which also increased the expression of markers for stem cell characteristics such as Oct4, Sox2, and CD133." (PMID 39776907, 2024). "Further, we also monitored OCT4 and SOX2 markers expression in normal pancreatic, and patient’s derived tumor tissues using immunohistochemistry (IHC) staining." (PMID 38429272, 2024). "In HNSCC, low SOX2 expression was correlated with poor clinical prognosis and with an increased migration of the tumor cells." (PMID 38275880, 2024). "Our results also showed that 5-FU a chemotherapy drug down regulated the expression of OCT4 and SOX2 in tumor organoids which was further confirmed by Flow Cytometry data." (PMID 38429272, 2024). "Meanwhile, silencing Sox2 markedly abrogated the sphere-forming ability of Notum-overexpressing MGC-803 cells, whereas Sox2 overexpression restored the tumor sphere formation inhibited by Notum knockdown." (PMID 37749430, 2024). "In a separate study, oligodendroglioma tumor-bearing mice “vaccinated” with SOX2 peptides in combination with temozolomide lived twice as long as both untreated mice and mice treated with temozolomide." (PMID 38612911, 2024). "Inhibition of PFKFB3 by PFK158 reduced the levels of several stemness markers, such as CD133 and SOX2; impeded glycolysis; and attenuated tumor growth in SCLC cell line-derived xenografts." (PMID 39456533, 2024). "Firstly, we have quantified the proportion of proliferative tumor cells (Sox2+ Ki67+) present in or around the resection cavity borders where we also quantified blood-derived macrophages CD68+ Galectine-3+ and microglia cells TMEM119+Galectine-3−." (PMID 39605004, 2024). "In this study, we performed a pan-cancer analysis of SOX2 using the TCGA, GETX, and TSIDB online databases and analyzed the expression of SOX2 in different tissues, tumor subtypes, and immune cells." (PMID 38164286, 2024). "SOX2 was upregulated on RNA sequencing in those tumours with low or patchy SF-1 expression when compared with those with diffuse SF-1 expression." (PMID 38483762, 2024). "In ESCC, the amplification of SOX2 not only reflects the selective maintenance of SOX2 expression in tumor cells but also promotes significant evolution of chromatin remodeling and the SOX2 cis‐regulatory element." (PMID 39184862, 2024). "Tsang and coworkers reported that tumor cells recruit dermal fibroblasts, fostering their expression of the stem cell marker Sox2 and activation into a CAF phenotype in a CCN2-dependent manner." (PMID 39199632, 2024). "Immunohistochemical staining of nude mouse subcutaneous tumor model of SOX2, CD44, CHI3L1, and CD24 in vivo shows the same result, and IHC staining of TAM markers CD68 had no obvious change." (PMID 39619148, 2024).